RN7SL453P (RNA, 7SL, cytoplasmic 453, pseudogene)
Gene: Miscellaneous RNA gene on chromosome 10 (47,692,399 to 47,692,727, reverse strand). Ensembl gene ENSG00000276544.
Homologues: Orthologues: chimpanzee Metazoa_SRP (99% identical), macaque Metazoa_SRP (95% identical). Paralogues in human: RN7SL248P (100% identical), RN7SL733P (98% identical), RN7SL33P (70% identical), RN7SL487P (68% identical), RN7SL775P (67% identical), RN7SL40P (67% identical), RN7SL526P (65% identical), RN7SL1 (65% identical), RN7SL317P (65% identical), Metazoa_SRP (65% identical), RN7SL2 (65% identical), RN7SL3 (64% identical), and 701 more.